RN7SL40P (RNA, 7SL, cytoplasmic 40, pseudogene)
Gene: Miscellaneous RNA gene on chromosome 2 (202,357,076 to 202,357,417, reverse strand). Ensembl gene ENSG00000242696.
Homologues: Orthologues: macaque Metazoa_SRP (84% identical), chimpanzee Metazoa_SRP (73% identical). Paralogues in human: RN7SL33P (72% identical), RN7SL317P (70% identical), RN7SL487P (70% identical), RN7SL775P (69% identical), RN7SL1 (68% identical), RN7SL2 (67% identical), RN7SL3 (67% identical), Metazoa_SRP (66% identical), RN7SL113P (66% identical), RN7SL49P (65% identical), RN7SL526P (65% identical), RN7SL408P (65% identical), and 698 more.